KMT2D (lysine methyltransferase 2D)
Diseases named in the same sentence as KMT2D in open-access papers (continued):
Sharing a sentence is not in itself a finding about the gene and the disease.
Kabuki syndrome (continued). "These are all predicted to introduce a premature translation termination codon with non-sense mediated decay resulting in a loss-of-function allele, making Kabuki syndrome, caused by haploinsufficiency of KMT2D, the most frequent single-gene disorder in this cohort." (PMID 30266093, 2018). "Kabuki syndrome is due to pathogenic mutation in KMT2D (lysine methyl transferase 2D)." (PMID 30542652, 2018). "It would be interesting to investigate cTfh cells in additional patients with KMT2A-associated WSS and KMT2D-associated Kabuki syndrome as this may help elucidate the underlying pathophysiology of the antibody deficiency." (PMID 28623346, 2017). "This approach has been used to identify causal genes and variants in rare Mendelian diseases: for example, exome sequencing of ten affected individuals with Kabuki syndrome identified the methyl transferase KMT2D (formerly MLL2) as causal, after substantial post hoc data filtering." (PMID 27305007, 2016). "Kabuki syndrome mutations C1430R and C1471Y reduce histone binding and catalytic activity of KMT2D." (PMID 26341229, 2015). "Recently, KMT2D has emerged as one of the most frequently mutated genes in a variety of cancers and in other human diseases, including lymphoma, medulloblastoma, gastric cancer, and Kabuki syndrome." (PMID 24240169, 2013). "In addition, heterozygous loss of the H3K4 methyltransferase Kmt2d that causes Kabuki Syndrome can be partially rescued in adult mice with a histone deacetylase inhibitor, but the reason that these models can be rescued at adult stages remains unknown." (PMID 40991443, 2025). "For example, CHARGE syndrome driven by CHD7, and Kabuki syndrome driven by MLL2/KMT2D/KDM6A both demonstrate fetal ear developmental abnormalities." (PMID 41020230, 2025). "The histone-modifying enzyme lysine methyltransferase 2D (KMT2D/MLL2) belongs to the most frequently mutated genes in cancer and is also known for its association with hereditary Kabuki syndrome." (PMID 41035915, 2025). "Patients with variants in KMT2A (Wiedemann-Steiner syndrome), KMT2C (Kleefstra syndrome) and KMT2D (Kabuki syndrome) display ID, microcephaly, epilepsy and short stature." (PMID 40568105, 2025). "We first observed this when studying variants in the genes for Kabuki syndrome 1 [MIM: 147920] and Kabuki syndrome 2 [MIM: 300867], KMT2D [MIM:602113] and KDM6A [MIM: 300128], respectively." (PMID 37022461, 2024). "In a mouse model of Kabuki syndrome, resulting from deficiency in the H3K4 lysine methyltransferase KMT2D, HDAC inhibition with AR-42 rescued structural and functional brain deficits." (PMID 38557491, 2024). "The heterogeneity of KMT2D variants, combined with the heterogenic clinical manifestations that make Kabuki syndrome difficult to diagnose, also suggest that KMT2D plays a much broader cellular role than its traditional function in chromatin modification." (PMID 39025450, 2024). "Zebrafish (Danio rerio) kmt2d null mutants displayed a complex phenotype that resembles the foremost features of Kabuki syndrome, including microcephaly, palate defects, abnormal ear development, and cardiac defects." (PMID 37504561, 2023). "Early on, a subpopulation of patients was misdiagnosed with Kabuki syndrome (KS; OMIM #147920), another multiple congenital anomaly syndrome that commonly presents with heart disease, which is caused by variants in KMT2D." (PMID 37504561, 2023). "In Kabuki syndrome, a multisystem disorder resulting in developmental abnormalities caused by mutations in KMT2D and KDM6A genes, approximately 60% of KMT2D mutations cause protein truncation resulting in loss of function." (PMID 37252797, 2023). "Few subjects also were tested for changes in KMT2D and KDM6A, the genes implicated in Kabuki Syndrome, as well as the epigenetic and genetic alterations of chromosome 11p15 implicated in Beckwith-Wiedemann Syndrome." (PMID 36389353, 2022).
Kabuki syndrome (continued). "The candidate genes identified in the Chinese cohort belonging to the early-pattern M1 included KMT2D, which encodes a histone modifier associated with CHD in Kabuki syndrome." (PMID 34905512, 2022). "Other examples of genes with multiple signatures are SRCAP (Floating Harbor syndrome and DEHMBA), KMT2D (Kabuki syndrome and CHARGE-like phenotype) and KAT6B (GTPTS and SBBYSS)." (PMID 35860466, 2022). "To further validate the specificity of the BOS DNAm signature generated, we classified three cohorts of individuals with Sotos, Weaver, and Kabuki syndromes, caused by variants in genes encoding the epigenetic regulators, NSD1, EZH2, and KMT2D, respectively." (PMID 35361921, 2022). "Pathogenic variants in the genes encoding the chromatin modifiers KMT2D and KDM6A are responsible for Kabuki syndrome 1 (KS1) and Kabuki syndrome 2 (KS2), respectively." (PMID 35384273, 2022). "The morphology of the eyes resembled Kabuki syndrome, but the KMT2D gene (MIM 602113) direct Sanger sequencing (performed in an external laboratory: Clinical Genomics Laboratory, Academic Hospital, Maastricht, The Netherlands) had negative results." (PMID 36553633, 2022). "The lysine methyltransferase 2D (KMT2D) protein is an important histone methyltransferase, whose encoding gene has been identified as the main causative factor of Kabuki syndrome (OMIM #147920)." (PMID 34724040, 2021). "Our study provides new insights into the role of KMT2D and histone methylation in dental development and furthers our understanding of the molecular pathogenesis of Kabuki syndrome." (PMID 34724040, 2021). "Epigenetic factors such as KMT2D and KDM6A are mutated in humans with Kabuki Syndrome, where a varying percentage of patients show cardiac defects." (PMID 34698193, 2021). "Four patients with Kabuki syndrome 1 (OMIM: 602113) (P52, P66, P70 and P71) had mutations in the KMT2D gene and demonstrated classic facial features and severe or recurrent infections during hospitalisation." (PMID 33777394, 2021). "Studies have shown that disruptions of the zebrafish orthologs, kmt2d and kdm6a, recapitulate phenotypes of Kabuki Syndrome." (PMID 34698193, 2021). "ATP7B-related Wilson disease and KMT2D-related Kabuki syndrome were observed in 3 (7.0%) and 2 (4.7%) patients, respectively." (PMID 34539730, 2021). "Methyltransferases have been shown to be responsible for episignatures in other neurodevelopmental disorders, e.g., DNMT3A in patients with Tatton–Brown–Rahman syndrome and KMT2D in Kabuki syndrome." (PMID 34445317, 2021). "Intriguingly, embryonic RNA in situ hybridization studies also localize Kmt2d expression to calvarial osteoblasts, further implicating the gene with the pathophysiology of craniosynostosis, a common finding in Kabuki syndrome patient s." (PMID 31924266, 2020). "Seven individuals with prominent extracardiac anomalies and developmental delay had disease-causing de novo variants, such as p.(Pro1747Argfs*49) in ANKRD11 (KBG syndrome), or p.(Arg5225Cys) in KMT2D (Kabuki syndrome)." (PMID 32037394, 2020). "Here, we generated and characterized zebrafish kmt2d null mutants that recapitulate the cardinal phenotypic features of Kabuki Syndrome, including microcephaly, palate defects, abnormal ear development, and cardiac defects." (PMID 31479440, 2019). "Our studies additionally defined phenotype-related accelerated and decelerated epigenetic aging in two histone methyltransferase disorders: NSD1 Sotos syndrome overgrowth disorder and KMT2D Kabuki syndrome growth impairment." (PMID 31160375, 2019). "Taken together, these findings demonstrate that Kmt2d regulates vasculogenesis and angiogenesis, provide evidence for interactions between Kmt2d and Notch signaling in Kabuki Syndrome, and suggest future directions for clinical research." (PMID 31479440, 2019). "Together, these data introduce a zebrafish kmt2d null mutant model and demonstrate its phenotypic and molecular utility as a model for studying Kabuki Syndrome." (PMID 31479440, 2019).
Kabuki syndrome (continued). "This study describes 5 novel variants of 7 KMT2D/KDM6A gene and summarizes the clinical manifestations and the mutational spectrum of 47 Chinese Kabuki syndrome (KS) patients." (PMID 31727177, 2019). "Deletion of KMT2D has been thought to be lethal, but here we describe a patient with KMT2D deletion and classical Kabuki syndrome phenotype." (PMID 31814321, 2019). "KMT2D, which encodes a histone H3K4 methyltransferase, has been implicated in human congenital heart disease in the context of Kabuki syndrome." (PMID 26932671, 2016). "Gene sequencing of KMT2D and KDM6A can be used to detect mutations in patients with a clinical diagnosis of Kabuki syndrome." (PMID 25896430, 2015). "Mutations in KMT2D, similar to those in KDM6A, are associated with Kabuki syndrome." (PMID 39941150, 2025). "Kabuki syndrome, caused by mutations in KDM6A or KMT2D, leads to developmental abnormalities." (PMID 39941150, 2025). "Subsequent studies have revealed that 9–14% of KMT2D-negative patients and <5% of patients with Kabuki syndrome presented with pathogenic variants in the KDM6A gene." (PMID 38667491, 2024). "AD and AR were the most common pattern of inheritance, and the most frequent variant genes were SLC4A1 and KMT2D, which can, respectively, lead to the two most frequent diseases: dRTA (with inclusion of SLC4A1, ATP6V1B1, and ATP6VOA4 genes) and Kabuki syndrome." (PMID 35612621, 2022). "Kabuki syndrome (KS) is a Mendelian Disorder of the Epigenetic Machinery (MDEM) caused by loss of function variants in either of two genes involved in the regulation of histone methylation, KMT2D (34–76%) or KDM6A (9–13%)." (PMID 36276984, 2022). "The anomalies of tooth number and crown morphology in Kabuki syndrome suggest that KMT2D might function in the formation and morphogenesis of dental enamel organ." (PMID 34724040, 2021). "By combining biochemical and metabolomic approaches in mouse and human cell models, we demonstrated a rewiring of the mitochondrial metabolic phenotype due to KMT2D alteration that might contribute to the onset of Kabuki syndrome." (PMID 32668765, 2020). "We present the first patient described with haploinsufficency of KMT2D leading to Kabuki syndrome." (PMID 31814321, 2019). "Because WDSTS can phenotypic overlap with Pierpont syndrome, Cornelia De Lange syndrome and Kabuki syndrome, the candidate genes causing the later three syndromes (i.e. TBL1XR1, NIPBL, SMC1A, SMC3, RAD21, HDAC8, KMT2D, and KMD6A) in our cohort have been excluded." (PMID 30305169, 2018). "Mutations of the chromatin modifiers, KMT2D and KDM6A, which encode for lysine (K)‐specific methyltransferase 2D and lysine‐specific demethylase 6A, cause Kabuki syndrome, a developmental disorder affecting the heart, brain, urogenital system, craniofacial structures, and linear growth (height)." (PMID 29523523, 2018). "Mutations in KMT2D (MIM 147920), NF1 (MIM 162200), and ZEB2 (MIM 235730) are known to cause human monogenic Mendelian syndromes (Kabuki syndrome, neurofibromatosis type 1, and Mowat-Wilson syndrome, respectively), and cardiac malformations in these syndromes occur in 3–50% of patients." (PMID 29089047, 2017). "KMT2D-related Kabuki syndrome (type 1) (OMIM# 147920) is inherited in an autosomal dominant manner and KMT2D mutations are present in 34–76 % of patients with KS, while KDM6A-related KS (type 2) (OMIM# 300867) is less frequent and inherited in an X-linked manner." (PMID 27699475, 2016). "It will also be important to establish whether KMT2D regulates ion homeostasis in other organ systems, and thus identify potential therapies for the multiple congenital anomalies observed in Kabuki syndrome." (PMID 26932671, 2016). "Interestingly, two of the presented candidate genes, KMT2D and KDM6A (a methyltransferase and a demethylase, respectively), regulate the chromatin methylation status and they are both causes of Kabuki syndrome, whose wide spectrum of features includes also OFCs and TA." (PMID 27699475, 2016).
Kabuki syndrome (continued). "This study provides a novel link between KMT2D function and NOTCH signaling, opening up new avenues for understanding the pathogenesis of congenital heart defects in Kabuki syndrome and potentially identifying new therapeutic targets." (PMID 38667491, 2024). "KMT2D was enriched in LVOTO, which is consistent with the reported spectrum of CHD in patients with Kabuki syndrome, where a large proportion of individuals have LVOTO type CHD." (PMID 34324492, 2021). "KMT2D and WDR5 defects are involved in Kabuki Syndrome characterized by multiple congenital abnormalities, from mild to severe developmental delay and intellectual disability." (PMID 28993790, 2017). "On the basis of these data, we speculate that KMT2D regulation of IRX5 and PHKG1 contributes to the pathogenesis of Kabuki syndrome." (PMID 27670201, 2016). "Despite KMT2D role in cancer has previously been described, no genetic data are available for previously reported Kabuki syndrome patients with tumors." (PMID 26341229, 2015). "Although Kabuki syndrome is a haploinsufficient, multi-organ syndrome in humans, our studies in cardiac-specific knockouts shed light on the primary nature of cardiac defects in the absence of KMT2D and uncover possible etiologies for CHDs in Kabuki syndrome patients." (PMID 26932671, 2016). "The role of KMT2D and/or KDM6A in the pathogenesis of Kabuki syndrome stems from a non-catalytic function in one or both of these proteins." (PMID 38857303, 2024).
lymphoma (50 papers, 2013 to 2025). A malignant (clonal) proliferation of B- lymphocytes or T- lymphocytes which involves the lymph nodes, bone marrow and/or extranodal sites. "As a prognostic biomarker and therapeutic target, the mutation status of KMT2D can serve as an indicator for prognosis assessment in lymphoma patients, with its mutations being associated with advanced disease, relapse risk, and poor prognosis." (PMID 41372946, 2025). "Another histone modifier recurrently mutated in GC-derived lymphomas is KMT2D, which monomethylates H3K4." (PMID 40512686, 2025). "Despite regulating overlapping gene enhancers and pathways, CREBBP and KMT2D mutations recurrently co-occur in germinal center (GC) B cell-derived lymphomas, suggesting potential oncogenic cooperation." (PMID 38570506, 2024). "Because KMT2D mutations have been largely associated with hematological malignancies, our initial studies focused on lymphoma and multiple myeloma cells." (PMID 39025450, 2024). "Other mutations include KMT2D missense and frameshift mutations, which appear in a variety of lymphomas." (PMID 37951851, 2024). "As for NGS, it would be recommendable to study differential mutational patterns in TCF3 and ID3, which are recurrently mutated in BL, and EZH2, CREBBP, and KMT2D, which are mutated in other lymphomas." (PMID 37672206, 2024). "This supports previous observations showing that KMT2D deficiency leads to inferior survival outcomes compared to KMT2D-proficient patients with lymphoma, lung, and breast cancers." (PMID 39578878, 2024). "A Kmt2dfl allele is available and when Kmt2d was deleted during early B cell development by Cd19Cre, the majority of Cd19Cre/wt;Kmt2dfl/fl mice died from lymphoma within 338 days." (PMID 38124747, 2023). "Of KMT2D’s missense mutations in lymphoma, several in the catalytic domain reduce KMT2D’s enzyme activity." (PMID 34194626, 2021). "It will be important to determine the extent to which KMT2D inactivating mutations support the glycolytic switch in GCB lymphomas." (PMID 35071240, 2021). "The KMT2D gene is mutated and deleted in many different types of cancer, including medulloblastoma, melanoma, lymphoma, leukemia, and lung, prostate, renal, bladder, ovarian, pancreatic, esophageal, and gastric cancers." (PMID 34194626, 2021). "Mutations in the KMT2D gene have been implicated in certain cancers, including medulloblastomas, lymphomas and lung cancer." (PMID 34336928, 2021). "ChIP-seq experiments were also performed in murine Kmt2d-deficient lymphomas and human KMT2D-mutant lymphoma cell lines (compared to wild-type) in order to map changes in H3K4me1/2 distribution and associated changes in gene expression." (PMID 33277464, 2020). "Overall, the results of these functional studies suggest a multifaceted role for the loss/inactivation of KMT2D in the progression of lymphoma, especially in FL and DLBCL." (PMID 33277464, 2020). "Herein, we report that combined haploinsufficiency of Crebbp and Kmt2d induces a more severe mouse lymphoma phenotype (vs either allele alone) and unexpectedly confers an immune evasive microenvironment manifesting as CD8+ T-cell exhaustion and reduced infiltration." (PMID 38570506, 2024). "KMT2D is regarded as a tumor suppressor, and its mutation leads to induction of lymphomas in mice." (PMID 37142644, 2023).